TNPO1 (transportin 1)
Description:
Functions in nuclear protein import as nuclear transport receptor. Serves as receptor for nuclear localization signals (NLS) in cargo substrates. May mediate docking of the importin/substrate complex to the nuclear pore complex (NPC) through binding to nucleoporin and the complex is subsequently translocated through the pore by an energy requiring, Ran-dependent mechanism. At the nucleoplasmic side of the NPC, Ran binds to the importin, the importin/substrate complex dissociates and importin is re-exported from the nucleus to the cytoplasm where GTP hydrolysis releases Ran. The directionality of nuclear import is thought to be conferred by an asymmetric distribution of the GTP- and GDP-bound forms of Ran between the cytoplasm and nucleus (By similarity). Involved in nuclear import of M9-containing proteins. In vitro, binds directly to the M9 region of the heterogeneous nuclear ribonucleoproteins (hnRNP), A1 and A2 and mediates their nuclear import. Involved in hnRNP A1/A2 nuclear export. Mediates the nuclear import of ribosomal proteins RPL23A, RPS7 and RPL5. In vitro, mediates nuclear import of H2A, H2B, H3 and H4 histones (By similarity). In vitro, mediates nuclear import of SRP19. Mediates nuclear import of ADAR/ADAR1 isoform 1 and isoform 5 in a RanGTP-dependent manner. Main mediator of PR-DUB complex component BAP1 nuclear import; acts redundantly with the karyopherins KPNA1 and KPNA2. (Microbial infection) In case of HIV-1 infection, binds and mediates the nuclear import of HIV-1 Rev.
Synonyms: MIP; KPNB2; MIP1; TRN; IPO2
Tractability: Small molecule: a structure with a bound ligand is known; it has a binding pocket of medium quality. PROTAC: ubiquitination databases record sites on it; its protein half-life has been measured.
Target class: Transporter
Gene: Protein-coding gene on chromosome 5 (72,816,312 to 72,916,741, forward strand). Ensembl gene ENSG00000083312.
Subcellular location: Cytoplasm; Nucleus
Subcellular location (Human Protein Atlas): Nucleoplasm; Cytoplasmic bodies; Cytosol; Nucleoli
Pathways (Reactome):
Cell Cycle: Postmitotic nuclear pore complex (NPC) reformation
Metabolism of RNA: Tristetraprolin (TTP, ZFP36) binds and destabilizes mRNA
Organelle biogenesis and maintenance: Intraflagellar transport
Gene Ontology:
Molecular function: protein binding; RNA binding; nuclear import signal receptor activity; nucleocytoplasmic carrier activity; small GTPase binding
Biological process: protein import into nucleus; intracellular protein transport
Cellular component: cytosol; extracellular exosome; nucleolus; nucleoplasm; cilium; cytoplasm; nucleus; nuclear lumen
Genetic constraint (gnomAD): Loss-of-function variants: 5 observed, 69.18 expected, observed/expected ratio (o/e) 0.0723, 90% interval 0.037 to 0.15. The upper end of that interval is the gene's LOEUF score, 0.15, which puts it in group 1 of 6, group 1 being the genes least tolerant of losing a copy. Missense variants: 381 observed, 752.08 expected, observed/expected ratio (o/e) 0.51, 90% interval 0.47 to 0.55. Synonymous variants: 246 observed, 256.47 expected, observed/expected ratio (o/e) 0.96, 90% interval 0.86 to 1.07.
Homologues: Orthologues: chimpanzee TNPO1 (100% identical), dog TNPO1 (100% identical), macaque TNPO1 (100% identical), pig TNPO1 (99% identical), mouse Tnpo1 (99% identical), rat Tnpo1 (95% identical), tropical clawed frog tnpo1 (95% identical), zebrafish tnpo1 (92% identical), guinea pig TNPO1 (90% identical), rabbit TNPO1 (89% identical), Drosophila melanogaster CG8219 (57% identical), Caenorhabditis elegans imb-2 (52% identical). Paralogues in human: TNPO2 (84% identical), IPO4 (19% identical), IPO5 (19% identical), RANBP6 (19% identical), KPNB1 (14% identical).
Diseases named in the same sentence as TNPO1 in open-access papers:
TNPO1 is named in the same sentence as 32 diseases in open-access papers, as found by Europe PMC text mining. Sharing a sentence is not in itself a finding about the gene and the disease. The quoted sentences say what the papers report.
esophageal cancer (5 papers, 2021 to 2025). A primary or metastatic malignant neoplasm involving the esophagus. "In addition, TNPO1 is identified as an oncogene and has been reported to be associated with the development of esophageal cancer and cervical cancer, consistent with our finding that TNPO1-knockdown inhibited proliferation of A549 cells." (PMID 36672460, 2023). "However, the detailed mechanism underlying TNPO1 in esophageal cancer is limited." (PMID 35840974, 2022). "Our research demonstrated that splicing factor QKI promotes circBCAR3 biogenesis, which accelerates esophageal cancer tumorigenesis via binding with miR-27a-3p to upregulate TNPO1." (PMID 35840974, 2022). "We found that circBCAR3 interacted with miR-27a-3p by the ceRNA mechanism to upregulate TNPO1 in esophageal cancer cells." (PMID 35840974, 2022). "At the cellular levels, TNPO1 reversed the inhibitory impacts of circBCAR3 knockdown on the proliferation, migration, invasion, and ferroptosis of esophageal cancer cells." (PMID 35840974, 2022). "Our further study will focus on the potential interaction of TNPO1 and carbonic anhydrase IX in hypoxic esophageal cancer." (PMID 35840974, 2022). "CircBCAR3 interacts with miR-27a-3p to upregulate TNPO1, thus exerting its biological functions in esophageal cancer cells." (PMID 35840974, 2022). "TNPO1 is significantly upregulated in six esophageal cancer cells compared with control Het-1A cell line." (PMID 35840974, 2022). "Our experimental results revealed that TNPO1 was upregulated in esophageal cancer tissues and showed positive expression correlation with QKI and E2F7." (PMID 35840974, 2022). "CircBCAR3 was found to interact with miR-27a-3p to upregulate transportin 1 (TNPO1) expression, promote esophageal cancer cell proliferation, migration, invasion and ferroptosis, and play an oncogenic role in esophageal cancer by promoting esophageal tumorigenesis and metastasis in mice." (PMID 37152286, 2023). "Hypoxia can induce the upregulation of TNPO1 in esophageal cancer cells." (PMID 35840974, 2022). "CircBCAR3 up-regulates transportin-1 (TNPO1) by combining with miR-27a-3p, which accelerates the tumorigenesis of esophageal cancer." (PMID 39866239, 2025). "We searched the GEPIA database to check the expression correlation between these key molecules in 182 esophageal cancer tissues and the results revealed a positive expression correlation between E2F7 and QKI, E2F7 and TNPO1, QKI and TNPO1." (PMID 35840974, 2022). "We also found that the expression of TNPO1 was higher in 182 esophageal cancer tissues than that in 286 adjacent non-tumor tissues from GEPIA database." (PMID 35840974, 2022). "PCR results showed TNPO1 was significantly high expressed in 45 esophageal carcinoma tissues compared to that in 45 adjacent non-tumor tissues." (PMID 35840974, 2022).
cervical cancer (4 papers, 2021 to 2023). A primary or metastatic malignant neoplasm involving the cervix. "Transportin-1 (TNPO1)-induced nuclear import of FUBP1 (Far upstream element binding protein 1) led to tumor immune evasion via upregulation of NRP1 in cervical cancer." (PMID 37704909, 2023). "Initially, their utility as biomarkers was suggested due to the detection of their protein content (KPNB1, CRM1, CAS, IPO5, and TNPO1) in the serum of patients with cervical cancer." (PMID 36992411, 2023).
breast carcinoma (3 papers, 2014 to 2023). "The association of the six top-ranked karyopherins (KPNA2, XPOT, CSEL1, KPNA1, KPNA4, and TNPO1) in the breast cancer datasets from Oncomine was analyzed using a Kaplan-Meier Plotter." (PMID 37928256, 2023).
ovarian carcinoma (3 papers, 2018 to 2023). A malignant neoplasm originating from the surface ovarian epithelium. "Moreover, TNPO1, ACLY, NME1, FLOT1, and KLC4 are proteins already known to be involved in epithelial ovarian cancer." (PMID 37775701, 2023).
prostate carcinoma (3 papers, 2013 to 2017). A carcinoma that arises from epithelial cells of the prostate gland. "Nevertheless, they do occur, as exemplified by a recently discovered gene fusion between IKK2 and TNPO1 (transportin 1), which resulted in elevated IKK2 expression levels in prostate cancer." (PMID 23915189, 2013). "A study indicated the presence of a TNPO1–IKBKB (IKK-beta) fusion in prostate cancer but not in benign tissue." (PMID 29312619, 2017).
colorectal cancer (2 papers, 2022 to 2025). A primary or metastatic malignant neoplasm that affects the colon or rectum. "For instance, elevated TNPO1 expression has been observed in colorectal cancer, where it correlates with enhanced tumor growth and poor prognosis." (PMID 40191195, 2025). "We next examined the dependence of β-catenin nuclear localization on TNPO1/2 in colorectal cancer cell lines, HCT-116 and DLD-1, which harbor an activating Ser45 β-catenin mutation and a deactivating frameshift mutation in APC, respectively." (PMID 36300792, 2022).
lung carcinoma (2 papers, 2023 to 2025). "Down-regulation of LNC EBLN3P expression caused the upregulation of miR-144-3p expression, which in turn caused the level of TNPO1 to increase, thereby inhibiting the viability and enhancing the radiosensitivity of lung cancer cells." (PMID 36672460, 2023). "After X-ray irradiation, the knockdown of LNC EBLN3P significantly decreased the protein expression of TNPO1 in lung cancer tissues compared with the control." (PMID 36672460, 2023). "According to bioinformatics predictions, down-regulated LNC EBLN3P may play an essential role in the carbon ion radiation-induced suppression of lung cancer by modulating the oncogene TNPO1, which is mediated by miR-144-3p." (PMID 36672460, 2023). "In summary, the lncRNA EBLN3P functions as a ceRNA to mediate lung cancer inhibition induced by carbon ion irradiation by sponging miR-144-3p to regulate TNPO1 expression, indicating that EBLN3P may be a promising target for increasing the treatment efficacy of conventional radiotherapy for NSCLC." (PMID 36672460, 2023).
atherosclerosis (1 paper, 2021). A disease characterized by the build-up of fatty material and calcium deposition in the arterial wall resulting in partial or complete occlusion of the arterial lumen. "A study showed that, TNPO1 may play an indispensable role in developing atherosclerosis by regulating the transport of CD44." (PMID 34138931, 2021).
COVID-19 (1 paper, 2022). A disease caused by infection with severe acute respiratory syndrome coronavirus 2. "In this study, six co-upregulated genes, RPS7, IGF1R, DICER1, ERH, MCTS1, and TNPO1, and two co-downregulated genes, FLNA and PXN, were identified from COVID-19 and thrombosis datasets." (PMID 35692833, 2022). "Based on bioinformatics analysis and previous studies, this study identified hub genes (RPS7, IGF1R, DICER1, ERH, MCTS1, TNPO1, FLNA, and PXN) that may contribute to the evaluation and treatment of COVID-19 and thrombosis." (PMID 35692833, 2022).
glioma (1 paper, 2022). A benign or malignant brain and spinal cord tumor that arises from glial cells (astrocytes, oligodendrocytes, ependymal cells). "The qRT-PCR results showed that the mRNA expression levels of FAM204A and SMU1 in human glioma cell lines overall showed a downward trend compared with the HA1800, while the mRNA expression levels of TNPO1 and TOP2A showed an overall upward trend." (PMID 35093128, 2022). "Compared with non-tumor tissues, FAM204A was down-regulated, but TNPO1 and TOP2A were up-regulated in glioma tissues." (PMID 35093128, 2022).
hepatocellular carcinoma (1 paper, 2025). A malignant tumor that arises from hepatocytes. "circBRWD1 demonstrated its ability in modulating the miR-1277/TRAF6 and miR-513a-5p/TNPO1 axes in osteoarthritis and hepatocellular carcinoma respectively." (PMID 41327336, 2025).
HIV-1 infection (1 paper, 2018). The type species of lentivirus and the etiologic agent of acquired immunodeficiency syndrome (AIDS). "Our results are in good general agreement with their findings that depletion of NUP214 or TNPO1 impair MX2 anti-viral function in HeLa cells, and also with the apparently variable nucleoporin requirements for HIV-1 infection and MX2 activity among different cell lines." (PMID 30496303, 2018).
lung adenocarcinoma (1 paper, 2023). A carcinoma that arises from the lung and is characterized by the presence of malignant glandular epithelial cells. "An analysis of the co-expression results indicated a positive correlation between LNC EBLN3P and TNPO1 in both lung adenocarcinoma and lung squamous carcinoma." (PMID 36672460, 2023).
melanoma (1 paper, 2025). A malignant, usually aggressive tumor composed of atypical, neoplastic melanocytes. "Moreover, TNPO1 has been linked to melanoma cell proliferation and metastasis through its regulation of nuclear import/export processes." (PMID 40191195, 2025).
meningoencephalitis (1 paper, 2022). Inflammation of the meninges and brain, generally secondary to an infectious cause. "TNPO1 (Transportin 1) is involved in checkpoint regulation and CDK-mediated phosphorylation and removal of Cdc6; mutation of TNPO1 leads to retinitis pigmentosa 2 and meningoencephalitis." (PMID 35466186, 2022).
metastatic prostate carcinoma (1 paper, 2015). A carcinoma that arises from the prostate gland and has spread to other anatomic sites. "Notably, CXCR4 was shown to undergo transportin 1-dependent nuclear localization in cancerous prostate tissues and established, metastatic prostate-cancer cell lines." (PMID 25884570, 2015).
cancer (9 papers, 2019 to 2025). A tumor composed of atypical neoplastic, often pleomorphic cells that invade other tissues. "Overexpression of TNPO1 has been linked to increased tumor cell proliferation and migration, contributing to aggressive cancer phenotypes." (PMID 40191195, 2025). "TMEM171 codes for a transmembrane protein that has been associated with different types of cancer, and TNPO1 codes for Transportin, a protein that participates in the nuclear transport of molecules." (PMID 38103737, 2024). "CircBCAR3 binds with miR-27a-3p to promote transportin-1 (TNPO1) expression, thus promoting cancer cell proliferation, migration, and invasion." (PMID 37065473, 2023). "Taken together, TNPO1/2 is required for β-catenin nuclear localization across a wide range of species: Xenopus, mouse, and human cancer cell lines." (PMID 36300792, 2022). "Binding to the C-terminal region of hnRNPA1, quercetin hindered hnRNPA1’s combination with transportin 1 (Tnpo1), leading to its cytoplasmic retention and subsequent recruitment of hnRNPA1 to stress granules (SGs), ultimately putting cancer cells on the path to apoptosis." (PMID 35879279, 2022). "Moreover, IGF1R, TNPO1 and FASN are experimentally validated targets for TFAP2A, as annotated by RegNetwork software, and are involved in multiple cancer stemness and drug resistance processes." (PMID 30944375, 2019).
tumor (9 papers, 2021 to 2025). "TNPO1 is a transport protein involved in nuclear-cytoplasmic trafficking which plays a critical role in regulating the cell cycle and is implicated in tumor cell proliferation and metastasis." (PMID 40191195, 2025). "As an oncogene, TNPO1 has been reported to be associated with tumor growth, invasion, and metastasis." (PMID 36672460, 2023). "For TNPO1, reports found that this gene was associated with protein localization and transport, inflammatory-immune response, and tumor immune evasion." (PMID 36591247, 2022). "By modulating the nuclear transport of signaling proteins, TNPO1 indirectly affects downstream signaling cascades that drive tumor growth and metastasis." (PMID 40191195, 2025). "In tumor cells, TNPO1 plays a pivotal role in the transport of transcription factors, splicing regulators, and other nuclear-localized proteins that govern gene expression and cellular behavior." (PMID 40191195, 2025). "TNPO1 influences tumor progression through its involvement in critical oncogenic signaling pathways." (PMID 40191195, 2025). "Through mechanistic experiments, we demonstrated that LNC EBLN3P/miR-144-3p/TNPO1 forms a ceRNA network and plays a crucial role in carbon ion-induced tumor growth inhibition." (PMID 36672460, 2023). "Additionally, TNPO1-mediated transport may contribute to the adaptation of tumor cells to their microenvironment, enhancing their ability to evade immune surveillance and thrive in metastatic sites." (PMID 40191195, 2025). "We selected four LLPS-related hub genes (FAM204A, SMU1, TNPO1 and TOP2A) involved in LPRS to test their transcript levels in cell lines, LGG tissues and non-tumor brain tissues." (PMID 35093128, 2022).
infection (4 papers, 2016 to 2025). The state of being infected such as from the introduction of a foreign agent such as serum, vaccine, antigenic substance or organism. "In contrast, ADAMTS18, CLN8, RDH10 and TNPO1 were shown to be up-regulated following infection in HSaVEC, indicating that gene regulation differs for these genes between the endothelial cells." (PMID 26837541, 2016). "MX2 also modestly enhanced HIV-1WT infection upon NUP62, RAE1, and TNPO1 knockdown." (PMID 39853118, 2025).
TNPO1 also shares sentences with these, for which no sentence is quoted: viral diseases (2 papers); Alzheimer disease (1); bladder cancer (1); digestive system neoplasm (1); frontotemporal dementia (1); hepatitis B (1); hepatitis C (1); measles (1); non-small cell lung carcinoma (1); osteoarthritis (1); osteoporosis (1); retinitis pigmentosa 2 (1); thrombosis (1).